MTOR (mechanistic target of rapamycin kinase)
Diseases named in the same sentence as MTOR in open-access papers (continued):
Sharing a sentence is not in itself a finding about the gene and the disease.
gastric cancer (777 papers, 2009 to 2026). A primary or metastatic malignant neoplasm involving the stomach. "Here, we used a genome-wide CRISPR-Cas9 screen to identify targets whose depletion, together with PI3K inhibition by alpelisib, blocked proliferation of an EBV-associated gastric carcinoma model with hyperactive PI3K/mTOR signaling." (PMID 41315365, 2025). "The insulin receptor (INSR) regulates the insulin signaling pathway and activates the oncogenic PI3K/Akt/mTOR pathway, and its high expression is inversely associated with patient survival in ccRCC and gastric cancer." (PMID 38673800, 2024). "The second generation mTOR inhibitor OSI-027 is used in phase I gastric cancer, causing a decrease in proliferation and antiangiogenetic capacities, and antitumor activity in several cancers such as the prostate, renal, and bladder." (PMID 37097377, 2023). "The glioma‐associated oncogene (GLI) related Akt–mTOR pathway directly affects the expression of PD‐L1 in the formation of the immunosuppressive environment of gastric cancer." (PMID 38045830, 2023). "The abnormal increase in the activity of the PI3K/Akt/mTOR pathway is associated with various malignancies; therefore, the modulation of this signaling pathway represents a new strategy, in particular in gastric cancer treatment." (PMID 37764304, 2023). "In gastric cancer patients, the higher activity of cytoplasmic mTOR was associated with poorer overall survival and relapse‐free survival." (PMID 35298869, 2022). "Dysregulational EGFR, KRAS, and mTOR pathways cause metabolic reprogramming, leading to progression of gastric cancer." (PMID 36145507, 2022). "In this study, we demonstrated that BLG26, a novel synthesized isaindigotone derivate, exhibited potential anti-proliferation effects on gastric cancer cells via causing apoptosis through PI3K/AKT/mTOR and mitochondrial pathway." (PMID 35887375, 2022). "Although the mTOR protein is mainly localized in cytoplasm, nuclear mTOR and its oncogenic impacts have been implicated in several tumors, including gastric cancer, endometrial cancer, thyroid cancer, PCa and multiple myeloma." (PMID 36077039, 2022). "Accordingly, several studies have identified nsSNPs within the mTOR gene to be associated with acute leukemia, colon cancer, gastric cancer, and many other types of cancer as well as with the risk of diabetes mellitus." (PMID 35788771, 2022). "The molecular characterization of gastric cancers has revealed that PI3K/AKT/mTOR pathway abnormalities are associated with a high recurrence rate of gastric cancer, suggesting that these molecules are potential therapeutic targets (2014)." (PMID 34135756, 2021). "Dysregulation of the phosphoinositide 3-kinase (PI3K)/AKT/mammalian target of rapamycin (mTOR) axis has been heavily implicated in tumorigenesis and the progression of numerous cancers, including lung, thyroid, ovarian and gastric cancer." (PMID 33801030, 2021). "It has been found that rottlerin suppressed cell growth, induced autophagy as well as apoptosis, and reduced migration in addition to invasion in SGC-7901 and MGC-803 GC gastric cancer cells through mTOR and S-phase kinase-associated protein 2 downregulation." (PMID 34572730, 2021). "Dysregulation of phosphatidylinositol-3 kinases (PI3K)/AKT/mTOR (mammalian target of rapamycin) signaling pathway has been recognized as the causative agent of gastric cancer pathogenesis." (PMID 29704890, 2019). "It has been reported that amplification and mutation of PI3K in gastric cancer are associated with the deregulation of the PI3K/Akt/mTOR pathway." (PMID 30274346, 2018). "Aberrant activation of the PI3K/AKT/mTOR signaling pathway through loss of the tumor suppressor PTEN protein or mutations in proteins in the PI3K/AKT pathway are extremely common in gastric cancer and other types of cancer." (PMID 30096805, 2018).
gastric cancer (continued). "Knockdown SLC1A5 in gastric cancer cells suppressed cell proliferation, caused G0/G1 arrest and inhibited cell invasion as well as migration partly by inactivated mTOR/p-70S6K1 signaling pathway in vitro." (PMID 29100325, 2017). "We observed frequently high expression of DDX5 and its strong association with p-mTOR in gastric cancer." (PMID 28216662, 2017). "Three MTOR missense mutations (N1421D, K1771R, I1973F) were found in patients with gastric cancer, angiosarcoma and renal cell carcinoma, respectively." (PMID 26859683, 2016). "Phosphorylated mTOR, indicating constitutive activation, has been associated with tumor progression and worse prognosis in gastric cancer patients." (PMID 25784931, 2015). "It has been reported that expression and functional activity of both mTOR and specific MMPs are associated with less favourable prognosis in gastric carcinoma, with overall heterogeneous results and stronger evidence for mTOR." (PMID 26652716, 2015). "We found that the transcription activity of T allele was higher than G allele with an approximately 1.5-fold in above four cell lines, suggesting that rs2295080 G allele worked as a defender for gastric cancer by reducing the transcription of mTOR." (PMID 23555892, 2013). "Distribution of genotypes of mTOR rs2295080 polymorphism between gastric cancer cases and healthy controls and the association with gastric cancer risk." (PMID 23555892, 2013). "Our research explored the relationship between single nucleotide polymorphism (SNP) rs2295080 in mTOR promoter region and the risk of gastric cancer (GC)." (PMID 23555892, 2013). "In conclusion, our study illuminated the mTOR rs2295080 locating in the promoter region of mTOR gene was significantly associated with risk of gastric cancer in a Chinese population." (PMID 23555892, 2013). "In conclusion, cytoplasmic p-mTOR expression was associated with tumour progression and poor survival in gastric cancer; the opposite results were obtained for nuclear p-mTOR expression." (PMID 19223902, 2009). "Besides, the Akt/mTOR pathway inactivation was demonstrated to be implicated in the autophagy initiation in αCLDN18.2-MMAE-treated gastric cancer cells." (PMID 39227365, 2024). "Moreover, the upregulation of PD-L1 via metastasis associated with colon cancer protein 1 (MACC1) implicated the activation of the Akt/mTOR pathway in gastric cancer cells." (PMID 37834467, 2023). "Furthermore, the increase in PD-L1 overexpression via neoadjuvant chemotherapy (NACT) in gastric cancer induced a decrease in the Akt/mTOR signaling cascade, which was associated with the initiation of autophagy." (PMID 37834467, 2023). "For instance, exosomal miR-107 modulated the HMGA2/mTOR/P-gp axis, drastically increasing the susceptibility of resistant gastric cancer cells to cisplatin, indicating that exosomal miR-107 may be a promising target in the therapy of gastric cancer." (PMID 37569598, 2023). "To verify this hypothesis, we analyzed the effect of PI3K/mTOR inhibition on signaling pathways in the PTEN-deficient gastric cancer HGC-27 cells using a phosphokinase array, which included antibodies against 43 phosphoproteins." (PMID 33431808, 2021). "In summary, these results strongly indicate that narciclasine-induced autophagy is associated with inhibiting the phosphorylation level of Akt/mTOR pathway in gastric cancer cells, thereby promoting apoptosis in gastric cancer cells and inhibiting cell proliferation." (PMID 34753517, 2021). "This indicated that berberine-mediated DDP-sensitivity of gastric cancer cells might be associated with inhibition of PI3K/AKT/mTOR signaling." (PMID 33362566, 2020). "It was reported that mTOR rs2295080 may be associated with susceptibility to gastric cancer in the Chinese population." (PMID 32597485, 2020). "Also, expression level of p-mTOR is inversely associated with disease-free survival time of gastric cancer." (PMID 32023262, 2020).
gastric cancer (continued). "We hypothesize that SPARC participates the regulations of paracrine actions in GCAFs, and the alterations of paracrine factors in CM cause the activation of AKT/mTOR in gastric cancer towards aberrant proliferation and anti-apoptosis." (PMID 31139014, 2019). "Moreover, patients with gastric cancer and renal cell cancer carrying the rs2295080 G allele showed decreased mTOR mRNA levels compared with those with the wild-type T allele." (PMID 27462867, 2016). "In gastric cancer, p-mTOR expression was closely linked to poor prognosis." (PMID 25680114, 2015). "In addition, mTOR rs2295080 was also shown to protect against gastric cancer risk in a Chinese population." (PMID 25654238, 2015). "The associations between mTOR rs22905080 polymorphism and clinical features of gastric cancer." (PMID 23555892, 2013). "Furthermore, mTOR has a prognostic value for lymph node metastasis, since its expression in metastatic lymph nodes is associated with poor clinical outcomes, but also a potential target for gastric cancer therapy." (PMID 40227324, 2025). "Thus, the Akt/mTOR pathway may be associated with both apoptosis and autophagy, and play a crucial role in SS-induced apoptosis and autophagy in gastric cancer cells." (PMID 33708631, 2021). "ADAMTS9 exerts an antitumor effect by inhibiting the phosphoinositide 3-kinase/protein kinase B/mammalian target of rapamycin (PI3K/AKT/mTOR) pathway in gastric cancer." (PMID 41517663, 2026). "For examples, epicatechin and epigallocatechin gallate (EGCG) regulate pathways such as NF-κB, MAPK, and PI3K, promoting apoptosis in cancer cells; EGCG also downregulates Akt/mTOR signaling in gastric carcinoma." (PMID 41511947, 2026). "In HER2-positive gastric cancer, sustained activation of mTOR via AKT/ERK pathways promotes chromatin remodeling and YAP-dependent metabolic adaptation, driving resistance to trastuzumab." (PMID 40276059, 2025). "A formononetin-coumarin hybrid compound, derived from formononetin, demonstrated anti-proliferative, tumor growth inhibitory, and anti-migratory properties against SGC7901 gastric cancer cells by modulating the Wnt/β-catenin and Akt/mTOR pathways." (PMID 40969409, 2025). "A previous study in gastric cancer patients demonstrated that TIGIT/CD155 signaling downregulates the PI3K-Akt-mTOR pathway in CD8+ T cells, leading to CD8+ T cell exhaustion." (PMID 39918313, 2025). "CircAKT3 is associated with gastric cancer targets and upregulates the autophagy pathway [PI3K/AKT/mechanistic target of rapamycin (mTOR)], helping promote cisplatin resistance." (PMID 41281941, 2025). "We previously reported that SUMOylation of TUFT1 is essential for AKT/mTOR pathway activation in gastric cancer cells." (PMID 41022752, 2025). "from China published an article entitled “Quercetin Induces Protective Autophagy in Gastric Cancer Cells: Involvement of Akt‐mTOR‐ and Hypoxia‐Induced Factor 1α‐Mediated Signaling” in the journal Autophagy, which has been cited 323 times." (PMID 40654535, 2025). "The PI3K/Akt/mTOR pathway was also studied by another team that found ties between Uro-A and both tumor suppression (in vivo) and the inhibition of gastric cancer (GC) cell proliferation and migration (in vitro)." (PMID 39857684, 2025). "Apigenin induces autophagy by inhibiting the activity of key molecules p-AKT and p-mTOR in gastric cancer cells, thereby enhancing the apoptotic ability of gastric cancer cells." (PMID 41220717, 2025). "The analysis revealed significant enrichment in FoxO signaling, PI3K-Akt signaling, mTOR signaling, as well as cancer-related pathways such as gastric cancer and acute myeloid leukemia." (PMID 41249093, 2025). "In gastric cancer, Narciclasine significantly improves survival rates by inducing autophagy-mediated apoptosis through the Akt/mTOR classic pathway." (PMID 41155419, 2025). "Apigenin has been discovered to stimulate AMPK–ULK1 activation while inhibiting mTOR, leading to autophagic cell death in gastric cancer." (PMID 40651979, 2025).
gastric cancer (continued). "When the organism is infected with Helicobacter pylori, the autophagy is suppressed through activating the PI3K/AKT/mTOR pathway, which promotes the growth and proliferation of gastric cancer cells." (PMID 40296912, 2025). "A latest investigation indicates that TSPAN9 boosts the resistance of gastric cancer cells to 5-FU by stimulating autophagy through the suppression of the PI3K/AKT/mTOR signaling pathway." (PMID 41347075, 2025). "The mTOR signaling pathway has also emerged as a significant player in the landscape of gastric cancer development." (PMID 40437566, 2025). "Inhibition of the ALDH1A3-mTOR axis with an mTOR inhibitor, temsirolimus, eradicated 5FU-tolerant gastric cancer cells." (PMID 41304766, 2025). "It has been demonstrated that Thymoquinone, a bioactive lactone produced by N. sativa seed oil (black cumin), stimulates death in gastric cancer cells through disrupting the PI3K/AKT/mTOR signaling system." (PMID 40717210, 2025). "Gastric stem cell abnormalities, particularly those driven by H. pylori infection and the dysregulation of signaling pathways such as Notch and mTOR, play substantial roles in the development of gastric cancer and related diseases." (PMID 40437566, 2025). "M2 TAMs in the TME were found to inhibit apoptosis and promote resistance to 5-fluorouracil (5-FU) by secreting CXC chemokine ligand 5 (CXCL5) and activating the PI3K/AKT/mTOR signaling pathway in gastric cancer cells." (PMID 39889181, 2025). "FABP6 is regulated by the transcription factor REST and participates in gastric cancer progression by influencing autophagy and the Akt/mTOR pathways." (PMID 41019085, 2025). "In gastric cancer, downregulation of CAF‐derived secreted protein acidic and rich in cysteine can lead to dedifferentiation of gastric cancer cells into CD44+/CD24− CSCs via AKT/mTOR signaling pathway." (PMID 41346572, 2025). "This induced autophagy-dependent cell death through inactivation of the PI3K/Akt/mTOR pathway in a dose-dependent manner in gastric cancer cells." (PMID 40559911, 2025). "Tempol treatment resulted in a significant reduction in the levels of phosphorylated ERK, JNK, AKT, and mTOR in both gastric cancer cells (CRL-1739-TPL) and colon cancer cells (CC-TPL) when compared to their respective control groups." (PMID 40729043, 2025). "The PI3K/AKT/mTOR pathway plays a vital role in the proliferation and survival of gastric cancer cells." (PMID 40729043, 2025). "In cellular experimental studies of a gastric cancer model, overexpression of KLF15 promotes apoptosis and autophagy through PI3K/Akt/ mTOR promoted apoptosis and autophagy, and inhibited the proliferation and invasion of gastric cancer cells." (PMID 40429972, 2025). "KEGG pathway analysis correlated with critical pathways, notably “Alzheimer’s disease,” “Pathways of neurodegeneration,” “Breast & Gastric cancer,” “Hippo signaling,” and “mTOR signaling pathway” mTOR signaling pathways." (PMID 41044153, 2025). "The published article titled “Knockdown of Rap1b Enhances Apoptosis and Autophagy in Gastric Cancer Cells via the PI3K/Akt/mTOR Pathway” has been retracted from Oncology Research, Vol." (PMID 40746886, 2025). "IGF‐1, an AKT agonist, and LY294002, an inhibitor, reversed the effects of KIRREL silencing and overexpression on the PI3K/AKT/mTOR pathway and on gastric cancer cell proliferation and angiogenesis." (PMID 37909722, 2024). "In this study, we found that gypenoside induced the apoptosis of gastric cancer cells through the PI3K/AKT/mTOR pathway." (PMID 38482051, 2024). "The study also revealed that aesculetin blocked the phosphatidylinositol-3-kinase (PI3K)/protein kinase B (AKT)/mammalian target of rapamycin (mTOR) pathway in gastric cancer cells." (PMID 38370475, 2024). "Highly expressed circNRIP1 in gastric cancer can act as the sponge of microRNA-149-5p to target AKT1/mTOR pathway and improve the glucose uptake capacity of gastric cancer cells." (PMID 38177102, 2024).
gastric cancer (continued). "LncRNA MALAT1 is one example in which silencing MALAT1 in gastric cancer cells triggered autophagy via mTOR inhibition, thereby suppressing cell proliferation." (PMID 39392103, 2024). "The immunosuppressive role of myeloid-derived suppressor cells (MDSC) has been studied by co-culturing gastric cancer organoids and immune cells, and the results suggest that PD-L1 expression is regulated by the gastric cancer mTOR signaling pathway." (PMID 39022082, 2024). "That down-regulation of Sema6D expression level can weaken ERK and PI3K/AKT/mTOR signaling pathways and thus inhibit gastric cancer cell proliferation, migration, and invasion." (PMID 40777970, 2024). "Previous studies have shown that Har promotes autophagy in gastric cancer cells and melanoma cells by inhibiting the Akt/mTOR/p70S6K pathway to exert antitumour effects." (PMID 38499622, 2024). "CircNRIP1 acts as a miR-149-5p sponge to promote gastric cancer progression via the AKT1/mTOR pathway." (PMID 38459596, 2024). "In summary, our findings indicate that gastric cancer cells inhibit the PI3K/AKT/mTOR pathway in CD8 + T cells by upregulating TIGIT expression on CD8 + T cells." (PMID 38216949, 2024). "Inhibition of Notch or mTOR signaling reduced the growth of human gastric cancer cell lines, indicating that both pathways are activated to promote gastric cancer cell proliferation." (PMID 38675376, 2024). "Circular RNA circNRIP1 acts as a sponge for microRNA-149-5p and promotes gastric cancer progression through the AKT1/mTOR pathway." (PMID 38459596, 2024). "In summary, gypenoside induced the apoptosis of HGC-27 and SGC-7901 gastric cancer cells by inhibiting the PI3K/AKT/mTOR pathway and enhancing the antitumor effects of T cells by inhibiting the expression of PD-L1." (PMID 38482051, 2024). "COE reduced the expression levels of Bcl-2, Bcl-xL, and the PI3K/Akt/mTOR/p70s6k signaling pathway proteins, while simultaneously enhancing the levels of Bax and caspase proteins in gastric cancer cells." (PMID 38633608, 2024). "Astragalus polysaccharides reduce the levels of p-AKT and p-mTOR in cells, block PI3K/AKT/mTOR signaling pathways, increase autophagy, and alleviate inflammation, to effectively suppress gastric cancer." (PMID 39210410, 2024). "EIF3B promotes tumor migration and metastasis by activating the PI3K/ AKT/ mTOR pathway during the development of gastric cancer." (PMID 38406279, 2024). "miR-375-3p overexpression reduces the proliferation and migration of GIST and gastric cancer cells via the AKT/mTOR signaling pathways." (PMID 38672573, 2024). "For example, by targeting pyruvate dehydrogenase kinase 1 (PDK1), the PI3K/AKT/mTOR signaling pathway can be effectively inhibited, thereby inducing mitochondria-dependent apoptotic mechanisms and providing a new strategy for gastric cancer treatment." (PMID 38654380, 2024). "A study found that baicalein enhanced the cisplatin sensitivity of SGC-7901/cisplatin gastric cancer cells by inducing apoptosis and autophagy via Akt/mTOR and Nrf2/Keap 1 pathways." (PMID 39539438, 2024). "Overexpression of RPS15A can activate the mTOR pathway and promote the proliferation of gastric cancer cells, thereby promoting the progression of gastric cancer." (PMID 39684863, 2024). "For example, circGSPT1, which is lowly expressed in gastric cancer, can encode GSPT1‐238aa protein, and the GSPase domain of GSPT1‐238aa protein can interact with the PI3K/Akt/mTOR signalling pathway." (PMID 38506082, 2024). "Thus, gastric cancer lymphangiogenesis may be associated with the Akt/mTOR-VEGF-C/VEGF-D axis." (PMID 39409942, 2024). "The PI3K/Akt/mTOR signaling pathway, a central regulator of cell growth, metabolism, and survival, is frequently activated in gastric cancer and precancerous lesions." (PMID 39906672, 2024). "miR-21 affects the PI3K/Akt/mTOR pathway to regulate cisplatin resistance and autophagy in gastric cancer." (PMID 38955795, 2024).